MSTN (myostatin)
Diseases named in the same sentence as MSTN in open-access papers (continued):
Sharing a sentence is not in itself a finding about the gene and the disease.
cardiomyopathy (10 papers, 2010 to 2023). A disease of the heart muscle or myocardium proper. "However, as myostatin is also present in cardiac tissue, myostatin targeted treatment may cause adverse events such as cardiomyopathy." (PMID 33807573, 2021). "In addition, myostatin is expressed in cardiac tissue, and sustained myostatin inhibition might cause cardiomyopathy." (PMID 34575048, 2021). "myofibrils-related cardiomyopathy, skeletal muscle fiber contraction, negative regulation of proteolysis, and follistatin-myostatin regulation were identified." (PMID 37468461, 2023). "Increased levels and activity of the TGF-β superfamily members, including TGF-β and activin isoforms, and myostatin, have been reported in patients with cardiomyopathy." (PMID 36269647, 2022). "Since many of these patients can be expected to experience some form of cardiomyopathy in the future, it is important to discern how myostatin inhibition will impact the injured heart." (PMID 20419100, 2010). "Since many of these patients can be expected to experience some form of cardiomyopathy in the future, it will be important to discern how myostatin inhibition will impact the injured heart." (PMID 20419100, 2010). "Muscle growth resulting from myostatin inactivation presumably creates an imbalance between the metabolic requirements of tissue cells and the previous perfusion capabilities of blood vessels, and CSRP3-encoded MLP may work to mediate this stress and reduce likelihood of cardiomyopathy." (PMID 25710176, 2015). "It would be interesting to know if the myostatin/AKT/FOXO pathway is responsible for the myocardial recovery that has been reported in non-ischemic forms of cardiomyopathy." (PMID 36143454, 2022). "Moreover, when the level of myostatin was compared in patients with and without cardiac symptoms, it turned out that DMD individuals with cardiomyopathy had significantly lower myostatin levels than patients without heart problems." (PMID 32691346, 2020).
inclusion body myositis (10 papers, 2010 to 2025). A slowly progressive degenerative inflammatory disorder of skeletal muscles characterized by late onset weakness of specific muscles and distinctive histopathological features. "Our results are in agreement with reports that myostatin causes sporadic inclusion body myositis (sIBM), a muscle-wasting disease that has pathogenesis similar to that of Alzheimer’s and Parkinson’s diseases." (PMID 25710176, 2015). "Myostatin, a negative regulator of muscle growth, has been implicated in sporadic inclusion body myositis (sIBM)." (PMID 20161792, 2010). "Furthermore, patients with inclusion body myositis show not only reduced myostatin expression levels in skeletal muscle but also an increased follistatin expression." (PMID 35922829, 2022). "However, interestingly, clinical trial on the use of bimagrumab, a monoclonal antibody against activin type II receptors that prevents binding of activin and myostatin, did not provide clinical benefits in terms of improvement in mobility in patients with inclusion body myositis." (PMID 40943287, 2025).
atherosclerosis (9 papers, 2013 to 2025). A disease characterized by the build-up of fatty material and calcium deposition in the arterial wall resulting in partial or complete occlusion of the arterial lumen. "Expression of MSTN in the media, neointima, plaque shoulder and infiltrating macrophages is implicated in the progression of atherosclerosis." (PMID 32157804, 2020). "Myostatin has a detrimental effect on vascular cells and contributes to atherosclerosis progression by favoring the migration of vascular smooth muscle cells (VSMCs) and the recruitment of monocytes, notably through MCP-1 upregulation in VMSCs and monocytes." (PMID 40278657, 2025). "In human, myostatin increases with the severity of atherosclerosis lesion of the aorta, where it localizes in the media–intima surface, primarily in VMSCs and infiltrating leukocytes." (PMID 40278657, 2025). "Another atherosclerosis-related molecule is the myokine MSTN." (PMID 39758846, 2024). "Exposure to myostatin disrupts the cytoskeletal structure and promotes the migration of VSMCs from the media layer to the intima layer of the arteries, a key mechanism contributing to the formation of atherosclerosis." (PMID 39727658, 2024). "Furthermore, VSMC myostatin, when stimulated by uremic toxins, can accelerate atherosclerosis and contribute to vascular cell aging in patients with CKD." (PMID 39727658, 2024). "Additionally, myostatin has been detected at various stages of atherosclerosis in the human aorta." (PMID 39727658, 2024). "However, despite evidence demonstrating the contribution of myostatin to the progression of atherosclerosis in humans and mice, no clinical study, to our knowledge, has investigated the relationship between myostatin levels and cardiovascular events in patients with CKD." (PMID 40278657, 2025).
Becker muscular dystrophy (9 papers, 2015 to 2025). Becker muscular dystrophy (BMD) is a neuromuscular disease characterized by progressive muscle wasting and weakness due to degeneration of skeletal, smooth and cardiac muscle. "In Becker muscular dystrophy, where a myostatin antagonist was delivered using an AAV, pre-treatment assessments such as MRI could facilitate gene transfer." (PMID 37240368, 2023). "Preclinical studies conducted in MSTN-null mdx mice, a model of DMD and Becker muscular dystrophy (BMD) featuring a premature stop codon in the gene for dystrophin, have demonstrated increased muscle size and strength." (PMID 39340593, 2025).
liver disease (9 papers, 2018 to 2025). "Myocytokines, including myostatin, irisin and vitamin D, may facilitate the progression of liver disease." (PMID 36618679, 2022). "Although this may seem initially contradictory to reported clinical reports of increased circulating myostatin levels in liver disease patients who present with muscle atrophy, our data suggest that muscle may not be the sole source of increased circulating Gdf8 observed in these patients." (PMID 37509548, 2023).
liver fibrosis (8 papers, 2019 to 2025). "Myostatin, a muscle-related protein, has also been implicated in liver fibrosis progression by activating hepatic stellate cells." (PMID 40433168, 2025). "Myostatin is an inhibitor of muscle growth and a promoter of liver fibrosis, but its levels are reduced in NAFLD patients with the practice of exercises." (PMID 37180779, 2023). "It has been reported that myostatin induces liver fibrosis by activating the JNK signaling pathway to activate hepatic stellate cells (HSC)." (PMID 36618679, 2022). "Myostatin aggravates hepatic fibrosis through activation of hepatic stellate cells via c-Jun n-terminal kinase activation." (PMID 33198216, 2020). "Regarding hepatic fibrosis, we evaluated the correlation between serum myostatin levels and hepatic fibrosis using the FIB-4 scores." (PMID 33198216, 2020). "In addition, patients with more advanced hepatic fibrosis had significantly higher serum myostatin than those with less advanced hepatic fibrosis." (PMID 33198216, 2020). "Levels of myostatin, which is associated with muscle atrophy and liver fibrosis, were higher in NAFLD subjects than in non-NAFLD subjects in the middle-age group." (PMID 31862937, 2019). "Third, we could not determine a direct relationship between serum myostatin levels and liver fibrosis progression because no paired data of transient elastography or liver biopsy during follow-up periods were available in this study." (PMID 33198216, 2020).
Skeletal muscle atrophy (8 papers, 2009 to 2024). The presence of skeletal muscular atrophy (which is also known as amyotrophy). "Considering that myostatin inhibition and physical activity are being explored as treatment options for muscle degeneration and other disorders, it is important to understand the impact of these factors at the gene co-regulation level." (PMID 25710176, 2015). "Cachexia from cancers and neurogenic muscle atrophy are also targets for myostatin inhibition." (PMID 19538713, 2009).
vitamin D deficiency (8 papers, 2020 to 2026). A nutritional condition produced by a deficiency of VITAMIN D in the diet, insufficient production of vitamin D in the skin, inadequate absorption of vitamin D from the diet, or abnormal conversion of vitamin D to its bioactive metabolites. "Third, VDR ablation and vitamin D deficiency may increase the myostatin levels." (PMID 34070910, 2021).
central obesity (7 papers, 2011 to 2022). "Lower serum myostatin independently associated with MetS, central obesity, low HDL cholesterol, and high TG after adjustment for age and gender." (PMID 25254550, 2014). "Lower serum myostatin independently associated with MetS, central obesity, low HDL-C, and high triglycerides after adjustment." (PMID 25254550, 2014). "In this study, we assessed the polymorphic status of the Myostatin gene and its correlation with the measures of generalized and abdominal obesity and LBM in Asian Indians residing in north India." (PMID 22916099, 2012). "Since myostatin was independently related to MetS, we estimated the odds ratio (OR) for metabolic disorders, including MetS, central obesity, low HDL cholesterol, hypertriglyceridemia, and DM, associated with different concentrations of myostatin in logistic regression models." (PMID 25254550, 2014). "Furthermore, those patients with higher serum myostatin had lower odds for MetS, central obesity, low HDL cholesterol, high TG, and DM after adjustment for age and gender." (PMID 25254550, 2014). "In the present study, K153R and A55T polymorphisms of the Myostatin gene was associated with generalized obesity, abdominal obesity and low LBM in non-diabetic Asian Indians." (PMID 22916099, 2012). "In a cross-sectional case-control study in young women with and without polycystic ovary syndrome (PCOS), elevated myostatin levels were positively correlated with increased waist circumference in women with PCOS which may be suggestive of an increased risk for abdominal obesity." (PMID 35287731, 2022). "The odds ratios for MetS, central obesity, low HDL-C, high triglycerides, and DM were 0.85, 0.88, 0.89, 0.85, and 0.92, respectively, when serum myostatin increased per 1 ng/mL, in the binary logistic regression models." (PMID 25254550, 2014).
COVID-19 (7 papers, 2021 to 2026). A disease caused by infection with severe acute respiratory syndrome coronavirus 2. "In the context of muscle-related biomarkers, elevated levels of myostatin and irisin were observed in patients experiencing fatigue, providing novel insights into the potential mechanisms underlying post-COVID-19 fatigue." (PMID 40458645, 2025). "Additionally, previous studies have associated increased myostatin levels to prolonged hospital stays during COVID-19, likely due to reduced physical activity during acute infection." (PMID 40458645, 2025). "The identification of altered biomarkers such as osteocalcin, PINP, ALP, OPN, COMP, HA, IGF-1, myostatin, follistatin, and creatine kinase can provide a foundation for developing minimally invasive diagnostic tools to detect early bone, cartilage, and muscle involvement in COVID-19 patients." (PMID 40943488, 2025). "Post-COVID-19 fatigue is strongly associated with prior ICU admission and elevated levels of myostatin and irisin, implicating potential myopathic mechanisms in its persistence." (PMID 40458645, 2025). "The objective of this study was to scrutinize the potential correlation between the levels of selected myokines (myostatin, agrin, irisin, and myonectin) and the duration of rehabilitation in post-COVID-19 patients." (PMID 38672190, 2024). "Many authors have suggested that the REST factor overexpression promoted by myostatin acts against metabolic glycemic control in COVID-19 patients." (PMID 37408184, 2023). "Similarly, muscle-related biomarkers, including IGF-1, myostatin, follistatin, and creatine kinase further highlight the profound impact of COVID-19 on skeletal muscle mass, function, and recovery potential." (PMID 40943488, 2025). "Key myokines such as myostatin, agrin, irisin, and myonectin may play pivotal roles in the pathogenesis, response to infection, and outcomes of COVID-19 patients." (PMID 38672190, 2024). "Considering that MPO, apelin, and myostatin showed consistent alteration patterns upon COVID-19, which is in line with their previously identified regulatory roles, we next explored the potential association between MPO, apelin, and myostatin and metabolic parameters." (PMID 34916489, 2021). "Taken together, these data suggest that COVID-19-associated metabolic abnormalities are at least partially dependent on the transcription factor REST and its downstream genes, which include MPO, apelin, and myostatin." (PMID 34916489, 2021).
dilated cardiomyopathy (7 papers, 2010 to 2023). Cardiomyopathy which is characterized by dilation and contractile dysfunction of the left and right ventricles. "In dilated cardiomyopathy, the myostatin mRNA expression increased about two-fold in each part of the myocardium, whereas the expression of ActRIIB remained unchanged." (PMID 38136649, 2023). "It is likely that the reduced supply of oxygen in ischemic cardiomyopathy prevents the activation of myostatin expression seen in dilated cardiomyopathy." (PMID 38136649, 2023). "One group employed Western blotting to detect elevated concentrations of the myostatin prodomain in the serum of 28 patients with dilated cardiomyopathy in comparison to 29 healthy controls." (PMID 24260393, 2013). "The aim of this study was to clarify whether the myostatin/AKT/FOXO pathway as well as the expression of MAFbx and MuRF1 are changed in dilated cardiomyopathy of ischemic origin (IDCM) and dilated cardiomyopathy of non-ischemic origin (NIDCM) compared to a control group." (PMID 36143454, 2022).
polycystic ovary syndrome (7 papers, 2021 to 2023). A disorder that manifests as multiple cysts on the ovaries. "Moreover, recent studies using clinical samples showed that myostatin may play an important role in the pathogenesis of several reproductive disorders such as uterine myoma, ovary hyperstimulation syndrome, and polycystic ovarian syndrome." (PMID 36901894, 2023). "Furthermore, data from clinical samples have highlighted the possible involvement of MSTN in the pathogenesis of certain ovary disorders, such as ovarian hyperstimulation syndrome (OHSS) and polycystic ovary syndrome ovaries (PCOS)." (PMID 35780124, 2022). "Furthermore, evidence from clinical samples has suggested that MSTN may have a role in the development of some reproductive diseases, such as uterine myoma, preeclampsia (PE), ovary hyperstimulation syndrome (OHSS), and polycystic ovarian syndrome (PCOS)." (PMID 35780124, 2022).
uremia (7 papers, 2018 to 2026). A clinical syndrome associated with the retention of renal waste products or uremic toxins in the blood. "In experimental uremia, the use of anti-myostatin peptibody for four weeks reversed weight loss and muscle wasting in mice by decreasing protein degradation, increasing protein synthesis and enhancing IGF-signaling and satellite cell function." (PMID 32876940, 2021). "This myostatin activation in CKD is caused by low physical activity, inflammation, uremia, angiotensin II, metabolic acidosis and glucocorticoid." (PMID 34299795, 2021). "Both studies suggest anti-catabolic and anti-inflammatory effects of myostatin inhibitors in experimental uremia." (PMID 32876940, 2021). "In the setting of uremia toxicity, the expression of myostatin has been described as increased, and it is therefore possible that patients with better kidney function or those who have been effectively treated have lower myostatin concentrations." (PMID 39125361, 2024). "Chronic inflammation, dysbiosis, uremia, and low physical activity all induce myostatin activation." (PMID 36287929, 2022). "Myostatin is a negative regulator of skeletal muscle mass, and an imbalance between IGF-1 and myostatin has been observed in experimental uremia models." (PMID 36632744, 2022).
dystocia (6 papers, 2021 to 2024). Slow or difficult obstetric labor or childbirth. "It should be mentioned that full knockouts of MSTN have also led to higher birth weights, which can result in dystocia problems, so more accurate MSTN mutations will probably be needed before this target can be used in real-world applications." (PMID 39166173, 2024). "For example, the famous “double-muscle” Belgian blue cattle, with a natural MSTN mutation, are often observed with dystocia, and homozygotes are more likely to exhibit such problems than the heterozygotes." (PMID 37065235, 2023). "In mammals, double-muscled cows with MSTN mutation have increased risk of dystocia due to heavier weight of their offspring, but the quality of semen has not been affected by MSTN mutant in pigs." (PMID 34209534, 2021). "The MSTN polymorphisms have negative effects on their reproductive traits, for example, calving difficulties (dystocia)." (PMID 37370404, 2023).
fibrosis (6 papers, 2013 to 2024). the formation of excess fibrous connective tissue in an organ or tissue in a reparative or reactive process. "Inhibition of MSTN was demonstrated to reverse muscle fibrosis by reducing fibroblasts’ resistance to the apoptosis." (PMID 39012095, 2024). "In this group of patients, an increase in pressure overload, expressed as a mean or peak gradient, was related to increases in LV fibrosis and myostatin and ceramides levels." (PMID 37958492, 2023). "The increase in myostatin does agree with similar changes we have found after treatment with MDSC of penile corporal fibrosis in T2D rats." (PMID 28217409, 2016). "Our study show that activated FAP-derived Fst and Fstl3 might block TGF-β and myostatin signaling, thereby promoting fast recovery of muscle in a fibrosis-free healthy way." (PMID 36411280, 2022). "In fibrosis patients the decrease in follistatin may result in an increase in activity of activin A and myostatin possibly suppressing the apoptosis that occurs in myofibroblasts after IR-induced damage has been repaired." (PMID 24204752, 2013).
gestational diabetes mellitus (6 papers, 2014 to 2024). "Higher serum myostatin levels were found in pregnant (16–20 gestational week) women, who later developed gestational diabetes mellitus, indicating a possible usage of myostatin as a gestational diabetes biomarker." (PMID 32796600, 2020). "In human placental explants treated with MSTN, deoxyglucose absorption was increased, suggesting that MSTN participates in placental glucose homeostasis and may be a therapeutic target in conditions ranging from placental insufficiency to gestational diabetes." (PMID 35780124, 2022). "Because several studies have documented that MSTN is related to placental glucose homeostasis, as previously stated, MSTN may also affect the generation of gestational diabetes mellitus (GDM)." (PMID 35780124, 2022). "The authors concluded that myostatin expression in placental tissue is altered under stress conditions (e.g., obesity and abnormal glucose metabolism) found in pregnancies complicated by gestational diabetes mellitus." (PMID 31817641, 2019). "On the other hand, gestational diabetes does not influence cord blood myostatin levels; however, it affects myostatin protein expression in placentae." (PMID 38398421, 2024). "In support of this view is the observation that activin A but not myostatin is increased in gestational diabetes." (PMID 25104880, 2014). "So far, there have been no studies on whether gestational diabetes mellitus (GDM) - a common pregnancy complication that has been associated with impaired fetal insulin sensitivity but enhanced fetal growth, may affect cord blood myostatin concentration." (PMID 36875483, 2023).